RHOC (ras homolog family member C)
Diseases named in the same sentence as RHOC in open-access papers (continued):
Sharing a sentence is not in itself a finding about the gene and the disease.
melanoma (continued). "One study using this approach demonstrated that the small GTPase RhoC was essential for the enhancement of melanoma metastasis when overexpressed." (PMID 12865923, 2003). "Recently, it was described that ectopic overexpression of RhoC in A375 melanoma cell line was sufficient to create a highly metastatic phenotype." (PMID 12177810, 2002). "Furthermore, plasma levels of atorvastatin, comparable to those used for the treatment of hypercholesterolemia, have been reported to inhibit the metastasis of human melanoma cells overexpressing RhoC in a xenograft model." (PMID 38540310, 2024). "RHOC expression has been found to associate with shorter disease‐free and overall survival in melanoma patients, but not as an independent predictor." (PMID 32053263, 2020). "Interestingly, DNA array analysis of metastatic melanoma cells revealed that RhoC was important for metastasis." (PMID 31340863, 2019). "QPCR results indicated that the expression of RhoA, RhoB and RhoC reduced in melanoma cells." (PMID 28404912, 2017). "RhoC depletion was previously reported to lower α5 integrin expression in melanoma cells." (PMID 25677806, 2015). "In addition, a strong correlation between RhoC over-expression and metastasis has been reported in lung, melanoma, breast and head and neck cancers." (PMID 24533098, 2014). "In addition, overexpression of RhoC promotes human melanoma cell invasion via the phosphatidylinositol-3 kinase (PI3K)/Akt signaling pathway." (PMID 23382905, 2013). "However, it should be noted that RhoC promotes invasion of human melanoma cells in a PI3K/Akt-dependent manner and promotes metastasis of prostrate cancer cells by activation of Pyk2, which regulates Akt phosphorylation." (PMID 19953094, 2010). "Furthermore, analysis of the phenotype of melanoma cells expressing dominant-negative Rho or RhoC indicated that RhoC is important in tumour cell invasion." (PMID 12865923, 2003). "Moreover, ectopic overexpression of the Rho protein RhoC in A375 melanoma cells was sufficient to create a highly metastatic phenotype." (PMID 12177810, 2002). "RHOC may also serve as a target for the cytotoxic T cells in patients with metastatic cancer, making it an interesting possible target for immunotherapy in melanoma." (PMID 32053263, 2020). "So far, a role for RhoC in bleb-based migration has not really been addressed, but it is relevant that RhoC is frequently upregulated in metastasis, and is associated with metastasis particularly in melanoma, which involves predominantly rounded bleb-driven migration." (PMID 26363959, 2015). "CD4+ T cell lines and clones generated from these two donors were indeed capable of killing the melanoma cell line FM3 which expresses endogenously both HLA-class II and the RhoC protein." (PMID 40333248, 2025). "First, Hynes and colleagues found markedly increased RhoC expression in the A375M2 cell line, which had been selected by twice isolating pulmonary metastases of the parental A375 melanoma line." (PMID 27600078, 2016). "In the same study, RhoC and FMNL2 were, by using RNA interference, found to be essential for the invasive motility of rounded human melanoma cells." (PMID 20633255, 2010). "Here, using three other human melanoma cell lines we have shown that RhoA, rather than RhoC, controls the migration and invasive capacities of melanoma cells through its positive regulation of melanoma-expressed CD70." (PMID 26828592, 2016). "On the other hand, RHOC has been identified as an overexpressed gene in metastatic murine and human melanoma cells in comparison with the non-metastatic parental cells." (PMID 18211678, 2008).
melanoma (continued). "Interestingly, while RhoC is an important player in the motility of inflammatory breast cancer (IBC) and melanoma, it does not contribute to motility in prostate cancer cell lines, such as PC-3." (PMID 31340863, 2019).
ovarian carcinoma (22 papers, 2004 to 2024). A malignant neoplasm originating from the surface ovarian epithelium. "Our previous studies found that RhoC expression was positively associated with many oncogenes in ovarian cancer, such as MMP2, BCL-xL and P70s6k." (PMID 28818073, 2017). "Our study found that high expression of the lncRNA ABHD11-AS1 in the ovarian cancer cell lines was associated with high expression of RhoC and its downstream molecules P70s6k, MMP2 and BCL-xL, while silencing of the lncRNA ABHD11-AS1 had the opposite effect." (PMID 28818073, 2017). "RhoC overexpression is associated with cell invasion and metastasis of ovarian cancer." (PMID 24986540, 2014). "For instance, overexpression of RhoC was found in metastatic lesions of inflammatory breast cancer and pancreatic ductal adenocarcinoma, and upregulation was associated with tumour progression in ovarian carcinoma." (PMID 15150600, 2004). "Circ_0013549 is produced from the RhoC (Ras Homolog Family Member C) gene, an oncogene in ovarian cancer." (PMID 37234708, 2023). "Coincidentally, PSD-95/Discs-large/ZO-1 homology (PDZ)-RhoGEF is also involved in RhoC activation in ovarian carcinoma." (PMID 34627249, 2021). "RhoC was observed as the target by miR-106b transfection, which suppressed tumor development and progression of epithelial ovarian cancer xenograft mouse models." (PMID 32443784, 2020). "Sang and colleagues found that tumor suppressive miR-519d or siRhoC co-transfection reversed E2F1 oncogenic effects in ovarian cancer cells (increased RhoC, Bcl-2, cyclin D1, survivin, MMP2, MMP9, STAT3, and HuR)." (PMID 32443784, 2020). "The purpose of this study was to explore the role and mechanism of action of circRhoC, a putative circRNA formed from RhoC, in ovarian cancer." (PMID 31639291, 2019). "LncRNA ABHD11-AS1 promoted ovarian cancer cell proliferation, invasion and metastasis, and inhibited ovarian cancer cell apoptosis by targeting RhoC and its downstream molecules." (PMID 30098599, 2018). "The E2F1/miR-519d/RhoC signaling pathway is of significant importance and shows promise as a target for diagnosing and treating ovarian carcinoma." (PMID 28146423, 2017). "After E2F1 plasmid transfection and E2F1-microRNA-519d (miR-519d)/si-RhoC (Ras homolog gene family member C) co-transfection, ovarian cancer cell phenotypes and the related molecules were examined in vitro and in vivo." (PMID 28146423, 2017). "All these findings together indicate that the lncRNA ABHD11-AS1 promotes the growth and metastasis of ovarian cancer cells by targeting RhoC." (PMID 28818073, 2017). "This study is the first to prove that the lncRNA ABHD11-AS1 promotes ovarian cancer cell proliferation, invasion and metastasis, and inhibits ovarian cancer cell apoptosis by targeting RhoC and its downstream molecules." (PMID 28818073, 2017). "We also used immunohistochemical analysis to verify that high expression of the lncRNA ABHD11-AS1 in ovarian cancer cells in in vivo tumors in nude mice led to an increase in RhoC expression." (PMID 28818073, 2017). "Silencing of RhoC in stable lncRNA ABHD11-AS1-overexpressing ovarian cancer cells resulted in a decrease in cancer cell proliferation, invasion and metastasis and an increase in cancer cell apoptosis." (PMID 28818073, 2017). "We provide evidence that E2F1/miR-519d/RhoC is a promising signaling pathway for diagnosing and treating ovarian carcinoma." (PMID 28146423, 2017). "This suggests that miR-519d has suppressive effects on ovarian carcinoma by downregulating RhoC, Bcl-2, cyclin D1, survivin, MMP2, MMP9, STAT3 and HuR expression." (PMID 28146423, 2017). "Ras homolog gene family member C (RhoC) is a vital RhoGTPase involved in cytoskeleton reorganization and cell adhesion and migration, especially in the regulation of ovarian cancer tumorigenesis and progression." (PMID 28818073, 2017). "In ovarian cancer, Ras homolog family member C (RhoC) overexpression promotes EMT and increased migration and invasion ability." (PMID 27829043, 2016).
ovarian carcinoma (continued). "In our previous study, we found that miR-93 downregulated RhoC to inhibit cell migration and invasion in ovarian cancer." (PMID 27829043, 2016). "In a previous study, we found that miR-93 downregulates RhoC to inhibit migration and invasion in ovarian cancer." (PMID 27829043, 2016). "Previously, we showed that RhoC expression correlated to clinical stage and vascularization in ovarian cancer." (PMID 25649143, 2015). "Here, we aimed to clarify the role of RhoC in EMT process of ovarian carcinoma, stimulated by TGF-β1 and VEGF." (PMID 24986540, 2014). "Previously, we found that the RhoC mRNA and protein were significantly higher in ovarian cancer, and correlated with clinicopathological staging." (PMID 24986540, 2014). "Moreover, research has demonstrated that the suppression of RhoC expression can impede the proliferation, drug resistance, invasion, and metastasis of stem cells in ovarian cancer." (PMID 39742265, 2024). "Downregulation of HOXD10 expression by miR-10b overexpression may induce an increase in prometastatic gene products, such as MMP14 and RHOC, and contribute to the acquisition of a metastatic phenotype by epithelial ovarian cancer cells." (PMID 36213580, 2022). "In HCC and epithelial ovarian cancer, miR-106b enhances cell migration by inducing RhoC expression." (PMID 34627249, 2021). "Furthermore, overexpression of miR-93-5P inhibited tumorigenesis and progression via targeting RhoC in epithelial ovarian cancer (OVCAR3, SKOV3/DDP, HO8910-PM) cells and OVCAR3 xenografts." (PMID 32443784, 2020). "Western blot showed that miR-519d transfection in ovarian carcinoma cells downregulated RhoC (Ras homolog gene family member C), Bcl-2, cyclin D1, survivin, MMP2, MMP9, STAT3 (signal transducer and activator of transcription 3), and HuR (ELAV-like RNA-binding protein 1) expression (P < 0.05)." (PMID 28146423, 2017). "Based on all these findings, it would be interesting to investigate whether RhoC plays a role in the development and progression of ovarian cancer." (PMID 28818073, 2017). "Further, silencing of the RhoC gene in lncRNA ABHD11-AS1-transfected ovarian cancer cells inhibited the tumor-promoting effect of ABHD11-AS1 (p < 0.05), promoted apoptosis of the cancer cells (p < 0.05), and inhibited tumor metastasis (p < 0.05) and invasion (Fig. 5dp < 0.05)." (PMID 28818073, 2017). "RhoC is a small G protein/guanosine triphosphatase closely involved in tumor invasion and metastasis, and could serve as a good biomarker of ovarian carcinoma differentiation and progression." (PMID 28146423, 2017). "We found that E2F1 plasmid and RhoC siRNA co-transfection greatly reversed the oncogenic role of E2F1 in ovarian carcinoma cell phenotype, revealing that RhoC plays a central role in the oncogenic regulation of E2F1/miR-519d on ovarian carcinogenesis and development." (PMID 28146423, 2017). "Previously, we showed that RhoC promoted ovarian cancer invasion and metastasis through MMP9." (PMID 25649143, 2015). "Our previous work showed that RhoC could promote the invasion and metastasis of ovarian cancer by affecting VEGF, MMP-9 and ROCK." (PMID 25933027, 2015). "Therefore, we performed further studies to explore the involvement of RhoC and miR-93-5P in ovarian cancer." (PMID 25649143, 2015). "Upregulated RhoC may affect ovarian carcinogenesis and should be considered a good biomarker of ovarian carcinoma differentiation and progression." (PMID 25649143, 2015). "Upregulated expression of RhoC is related to the metastasis and invasiveness of many kinds of human malignant tumors, such as non-small cell lung carcinoma and hepatocellular carcinoma cells and is correlated with a poorer prognosis in patients with pancreatic adenocarcinoma and ovarian carcinoma." (PMID 26673619, 2016). "In ovarian cancer, miR-519d directly binds to and inhibits the expression of the 3′UTR of RhoC mRNA." (PMID 34627249, 2021).
ovarian carcinoma (continued). "In conclusion, our study identifies a novel molecular mechanism for E2F1, whereby it targets miR-519d to upregulate RhoC, Bcl-2, cyclin D1, survivin, MMP2, MMP9, STAT3 and HuR expression, promoting tumorigenesis and progression in ovarian carcinoma." (PMID 28146423, 2017). "In ovarian cancer, RhoC overexpression promotes EMT, invasion, and metastasis, and RhoC knockout reverses the promoter role of vascular endothelial growth factor (VEGF) and transforming growth factor (TGF) in EMT." (PMID 27829043, 2016). "Another study showed that decreased HOXD10 expression caused by miR-10b overexpression might trigger synthesis of pro-metastatic molecules, such as RhoC and MMP14 and thus contribute to the acquisition of metastatic phenotypes in different epithelial ovarian cancer cell lines." (PMID 32443784, 2020). "In conclusion, the oncogenic effect of RhoC in ovarian cancer is at least in part due to circRhoC, which functions not only as a miR‐302e sponge to positively regulate VEGFA protein expression, but may also directly bind and modulate VEGFA expression." (PMID 31639291, 2019). "We describe a novel molecular mechanism by which RhoC forms a circRNA that not only sponges miR‐302e to positively regulate VEGFA, but may also directly bind and modulate VEGFA expression, which may promote tumorigenicity and progression in ovarian cancer." (PMID 31639291, 2019). "Furthermore both VEGF and TGF-β1 could be responsible for aberrant expression of Ras homolog gene family, member C (RhoC), which is involved in the EMT of ovarian cancer cells." (PMID 26356073, 2015). "However, several studies suggested that RhoC functions independently of ROCK signaling and a recent study reported that RhoC suppresses MLC2 phosphorylation in response to LPA in osteosarcoma and ovarian cancer cells." (PMID 23825001, 2013).
prostate carcinoma (17 papers, 2011 to 2025). A carcinoma that arises from epithelial cells of the prostate gland. "In a recent study, prostate carcinoma patients were vaccinated with a single 20 aa EP (derived from the RhoC tumor antigen) emulsified in Montanide." (PMID 36359847, 2022). "A phase I/II clinical trial showed that a vaccine targeting RHOC was well tolerated and safe in prostate cancer patients, induced effective and durable T-cell immunity, and delayed tumor metastasis and recurrence." (PMID 36439479, 2022). "The expression and localization of E-cadherin are deranged by activated RhoC in prostate cancer cell." (PMID 34627249, 2021). "On the other hand, in prostate cancer cells, it is RhoC and ROCK signaling that is essential for interaction with endothelial cells, promoting adhesion and paracellular extravasation." (PMID 27158478, 2016). "In the present study, we used mRNA microarray analysis in the RhoC-dependent aggressive PC-3 human prostate cancer cell line to show that CCG-1423 does effectively perturb Rho-regulated transcription pathways." (PMID 27600078, 2016). "RhoC depletion by RNAi reduces PC3 prostate cancer cell adhesion to ECs, intercalation between ECs as well as transendothelial migration in vitro." (PMID 25677806, 2015). "In prostate cancer, RhoC promotes tumor metastasis by sequential activation of Pyk2, focal adhesion kinase (FAK), mitogen-activated protein kinase (MAPK) and Akt, followed by the upregulation of MMP2 and MMP9, resulting in the induction of tumor cell invasion." (PMID 23382905, 2013). "Phase I/II trial of synthetic long-peptide vaccine targeting RhoC in patients with prostate cancer." (PMID 40438385, 2025). "Besides, two potential therapeutic targets, BIRC5 and RHOC, were identified by us in prostate cancer." (PMID 36439479, 2022). "RhoC is increasingly reported to be involved in the malignant potential of tumors, such as breast cancer, lung cancer, gastric cancer, colon cancer, prostate cancer, and head and neck squamous cell carcinoma (HNSCC)." (PMID 33519932, 2021). "A recent study on prostate cancer has excitingly announced that vaccination against RhoC could potentially delay or prevent cancer recurrence and metastasis." (PMID 34627249, 2021). "Type I collagen could mediate the prostate cancer invasion through RhoC GTPase and integrin α2β1 signals." (PMID 34319913, 2021). "Furthermore, RhoA and RhoC have been shown to drive adhesion to the endothelium and transendothelial migration in breast and prostate cancer cells." (PMID 27158478, 2016). "Previously, we demonstrated that RhoC GTPase was required for PC-3 prostate cancer cell invasion." (PMID 21776386, 2011). "Thus, we envisioned that the targeting of RhoC in vaccination could lead to the selective eradication of prostate cancer cells with metastatic potential." (PMID 40333248, 2025). "Thus, the drugs targeting BIRC5 and RHOC may be potential targets in the treatment of prostate cancer." (PMID 36439479, 2022). "Also, Pyk2 was responsible for RhoC-triggered MAPK signaling for prostate cancer progression." (PMID 31387985, 2019). "Moreover, in prostate cancer cells, RhoC activates matrix metallo‐proteinases 2 and 9 (MMP2 and MMP9) in vitro, which could contribute to invasion." (PMID 25677806, 2015). "RhoC has also been shown to activate the Protein-Tyrosine Kinase 2 (PYK2) pathway in prostate cancer, consequently leading to metastasis in prostate cancer." (PMID 31340863, 2019). "Conversely, in a prostate cancer study, RhoC expression did not contribute to cell motility but only promoted cell invasion." (PMID 33519932, 2021). "An increase in RhoC GTPase was shown to increase the invasion of PC3 prostate cancer cells without affecting the motility." (PMID 28371345, 2017).